MTNR1A (melatonin receptor 1A)
Description:
High affinity receptor for melatonin. Likely to mediate the reproductive and circadian actions of melatonin. The activity of this receptor is mediated by pertussis toxin sensitive G proteins that inhibit adenylate cyclase activity. Possibly involved in sleep induction, by melatonin activation of the potassium channel KCNMA1/BK and the dissociation of G-beta and G-gamma subunits, thereby decreasing synaptic transmission (By similarity).
Synonyms: Mel-1A-R; MT1
Tractability: Small molecule: an approved drug acts on it; a structure with a bound ligand is known; a high-quality ligand is known; it belongs to a druggable protein family. Antibody: its Gene Ontology location is reachable by antibodies, with high confidence; UniProt places it where antibodies can reach, with medium confidence; UniProt predicts a signal peptide or a membrane-spanning region. PROTAC: a small molecule that binds it is known.
Target class: Membrane receptor; Family A G protein-coupled receptor; Monoamine-derivative receptor (family A GPCR); Melatonin receptor; Small molecule receptor (family A GPCR)
Chemical probes: S26131, UCSF7447 (high quality), UMBELLIPRENIN
Gene: Protein-coding gene on chromosome 4 (186,526,792 to 186,555,567, reverse strand). Ensembl gene ENSG00000168412.
Subcellular location: Cell membrane
Pathways (Reactome):
Signal Transduction: Class A/1 (Rhodopsin-like receptors); G alpha (i) signalling events
Gene Ontology:
Molecular function: hormone binding; melatonin receptor activity; protein binding; G protein-coupled receptor activity
Biological process: adenylate cyclase-inhibiting G protein-coupled receptor signaling pathway; circadian rhythm; G protein-coupled receptor signaling pathway, coupled to cyclic nucleotide second messenger; mating behavior; G protein-coupled receptor signaling pathway
Cellular component: plasma membrane; receptor complex; membrane
Genetic constraint (gnomAD): Loss-of-function variants: 11 observed, 8.03 expected, observed/expected ratio (o/e) 1.37, 90% interval 0.84 to 1.9. That is too few expected variants to judge how well the gene tolerates losing a copy. Missense variants: 441 observed, 467.25 expected, observed/expected ratio (o/e) 0.94, 90% interval 0.87 to 1.02. Synonymous variants: 196 observed, 204.21 expected, observed/expected ratio (o/e) 0.96, 90% interval 0.85 to 1.08.
Homologues: Orthologues: chimpanzee MTNR1A (99% identical), macaque MTNR1A (95% identical), dog MTNR1A (88% identical), guinea pig MTNR1A (87% identical), mouse Mtnr1a (85% identical), rat Mtnr1a (85% identical), pig MTNR1A (83% identical), tropical clawed frog mtnr1a (77% identical), zebrafish mtnr1ab (77% identical), rabbit MTNR1A (76% identical). Paralogues in human: MTNR1B (58% identical), GPR50 (48% identical), PRLHR (24% identical), TACR3 (24% identical), GPR83 (23% identical), NPY2R (23% identical), NPY1R (23% identical), TACR1 (22% identical), MCHR1 (21% identical), TACR2 (21% identical), GPR75 (20% identical), NPY4R (20% identical), and 21 more.
Diseases named in the same sentence as MTNR1A in open-access papers:
MTNR1A is named in the same sentence as 63 diseases in open-access papers, as found by Europe PMC text mining. Sharing a sentence is not in itself a finding about the gene and the disease. The quoted sentences say what the papers report.
oral cancer (9 papers, 2012 to 2024). "The MTNR1A polymorphic variants show important synergistic influence on the oral cancer development in patients with underlying risk factors for the disease such as betel quid chewing and smoking." (PMID 35008896, 2021). "Oral cancer patients who habitually chewed betel nut and carried the T/T allele of MTNR1A rs13140012, were more prone to develop lymph node metastasis and late-stage tumors." (PMID 29163852, 2017). "Gene-environment interactions of variants in MTNR1A and smoking have been reported in relation to oral cancer." (PMID 27688819, 2016). "In the present study, betel quid-chewing oral-cancer patients with the MTNR1A rs13140012 T/T mutation type had higher risks for developing advanced clinical stage and lymph node metastasis than those with the WT." (PMID 25806809, 2015). "In this study, we provide novel information of MTNR1A SNPs with oral cancer susceptibility, interactions with environmental risk factors, and associations with clinicopathologic statuses." (PMID 25806809, 2015). "Adjusted odds ratios (ORs, AORs) and 95% confidence intervals (CIs) of clinical statuses associated with genotypic frequencies of MTNR1A rs13140012 in oral cancer among 478 betel quid chewers." (PMID 25806809, 2015). "In summary, to our knowledge, this is the first study to show the statistical association among the MTNR1A polymorphism, betel quid-chewing and tobacco smoking habits, and the susceptibility to oral cancer development." (PMID 25806809, 2015). "We analyzed contributions of different haplotype combinations of 3 MTNR1A SNPs (rs2119882, rs13140012, and rs6553010) to the risk of oral cancer and eventually found that the CTA haplotype showed a high risk for OSCC." (PMID 25806809, 2015). "Betel quid-chewing oral-cancer patients with the MTNR1A rs13140012 T/T polymorphism had a higher risk of developing an advanced clinical stage and neck lymph node metastasis than WT carriers." (PMID 25806809, 2015). "The current study investigated relationships between SNPs (rs2119882) in the promoter and intron (rs13140012 and rs6553010) regions of the MTNR1A gene and the risk of oral cancer." (PMID 25806809, 2015). "The synergistic effects of environmental factors (betel quid chewing and cigarette smoking) and MTNR1A gene polymorphisms on the risk of oral cancer are well demonstrated." (PMID 25806809, 2015). "Adjusted odds ratios (ORs, AORs) and 95% confidence interval (CIs) of oral cancer associated with MTNR1A genotypic frequencies and smokers among 571 betel nut consumers." (PMID 25806809, 2015). "Although evidence exists supporting MTNR1A having a tumor-suppressive effect, little is known about the association between genetic polymorphisms of MTNR1A and the risk of oral cancer." (PMID 25806809, 2015). "Adjusted odds ratios (ORs, AORs) and 95% confidence intervals (CIs) of oral cancer associated with MTNR1A genotypic frequencies and betel nut chewing among 748 smokers." (PMID 25806809, 2015). "The CTA haplotype of the studied MTNR1A polymorphisms (rs2119882, rs13140012, rs6553010) was related to a higher risk of oral cancer." (PMID 25806809, 2015). "Notably, MTNR1A gene polymorphism has been closely linked to various diseases, including oral cancer, polycystic ovary syndrome, type 2 diabetes, and Alzheimer’s disease." (PMID 38440074, 2024). "Moreover, MTNR1A gene polymorphisms exhibited synergistic effects of environmental factors (betel quid and tobacco use) on the susceptibility of oral cancer." (PMID 25806809, 2015). "Finally, oral-cancer patients with betel quid-chewing habit who had T/T allele of MTNR1A rs13140012 were at higher risk for developing an advanced clinical stage and lymph node metastasis." (PMID 25806809, 2015).
oral cancer (continued). "A significant association between MTNR1A polymorphisms and oral carcinogenesis has been demonstrated, in which environmental factors (betel quid chewing and cigarette smoking) are required to increase the susceptibility to oral cancer in individuals with MTNR1A gene polymorphisms." (PMID 27023475, 2016). "Alleles with the highest distribution frequencies for rs2119882, rs13140012, and rs6553010 genotys of MTNR1A in both recruited oral cancer patients and healthy controls were heterozygous T/C, heterozygous A/T, and homozygous A/A, respectively." (PMID 25806809, 2015). "The purpose of this study was to explore the combined effect of melatonin receptor type 1A (MTNR1A) gene polymorphisms and exposure to environmental carcinogens on the susceptibility and clinicopathological characteristics of oral cancer." (PMID 25806809, 2015). "Additionally, the functional cancellation by hypermethylation of melatonin receptor 1A gene suggests melatonin signaling as tumor suppressive in oral cancer." (PMID 31684096, 2019). "With regard to oral cancer, it has been speculated that the restoration of melatonin receptor 1a expression, in an exogenous way, inhibits the growth of oral squamous cell carcinoma." (PMID 28422058, 2017). "In our study, MTNR1A gene SNPs (rs2119882, rs13140012, and rs6553010) alone did not contribute to oral-cancer susceptibility." (PMID 25806809, 2015). "Distribution frequencies of the MTNR1A haplotype in controls and oral cancer patients." (PMID 25806809, 2015). "Three polymorphisms of the MTNR1A gene from 618 patients with oral cancer and 560 non-cancer controls were analyzed by real-time polymerase chain reaction (PCR)." (PMID 25806809, 2015). "Distribution frequencies of MTNR1A genotypes in 560 controls and 618 oral-cancer patients." (PMID 25806809, 2015). "In relation to oral cancer, it has been speculated that exogenous restoration of melatonin receptor 1 A (MTNR1A) expression inhibited the growth of oral squamous cell carcinoma cells lacking its expression." (PMID 22792106, 2012). "In OSCC, melatonin and MTNR1A were reported to exhibit growth-suppressive activity and found that the MTNR1A gene is usually downregulated or silenced through epigenetic regulation; however, there have been no studies on the relationship between genetic regulation of the MTNR1A gene and oral cancer." (PMID 25806809, 2015). "Moreover, people who were either polymorphic for MTNR1A in rs2119882 or who smoked were at a 12.95-fold risk (p < 0.05) of developing oral cancer, compared to people with the WT gene who did not smoke." (PMID 25806809, 2015).
breast carcinoma (8 papers, 2013 to 2023). "According to a large Korean study the MTNR1A rs2119882 T>C C allele carriers show significantly decreased breast cancer risk in comparison to other women." (PMID 35008896, 2021). "Analysis of MTNR1A rs2119882 demonstrated a decreased risk of breast cancer in CC compared to TT (p-FDR = 0.043)." (PMID 31358835, 2019). "With the cut-off point for P-value at 0.05 using permutation test, three SNPs including rs11133373 and rs3749474 in the CLOCK gene, and rs2119882 in the MTNR1A gene have a statistically significant association with breast cancer." (PMID 31358835, 2019). "The variant alleles of MTNR1A rs113113549 polymorphisms were associated with decreased risk of breast cancer in the women with three consecutive night shifts." (PMID 23822714, 2013). "In the subjects with three night shifts, SNPs in BMAL1 (rs2278749), BMAL2 (rs2306074), CSNK1E (rs5757037), NPAS2 (rs17024926), PER3 (rs1012477) and MTNR1A (rs131113549) were associated with decreased breast cancer risk." (PMID 23822714, 2013). "The results show that only one of the investigated MTNR1A polymorphisms might modulate the breast cancer risk." (PMID 35008896, 2021). "However, our study demonstrates that MTNR1A rs2119882 CT and TT genotype decreased breast cancer risk." (PMID 31358835, 2019). "Common variants in MTNR1A may contribute to breast cancer susceptibility." (PMID 35565484, 2022). "The frequencies of the genotypes and allelotypes of SNP rs2119882 for the MTNR1A gene significantly differ between patients with polycystic ovary syndrome and healthy controls, while another SNP in the MTNR1A gene, rs7665392, may contribute to breast cancer susceptibility." (PMID 29163852, 2017). "Our results demonstrated that nucleolar and spindle-associated protein 1 (NUSAP1), melatonin receptor 1A (MELT), and cyclin-dependent kinase 1 (CDK1) are three hub genes that play pivotal roles in the pathogenesis of breast cancer." (PMID 38084295, 2023). "Our study results support a putative role of several loci in circadian genes (CLOCK, TIMELESS) and genes of melatonin biosynthesis (MTNR1A) in the development of breast cancer." (PMID 31358835, 2019). "In the genes controlling melatonin biosynthesis (AANAT) or melatonin receptors (MTNR1A and MTNR1B), several SNPs were associated with increased risk of breast cancer." (PMID 23822714, 2013). "In subjects with three consecutive night shifts, the odds of reduced risk of breast cancer associated with carriage of variant alleles of SNPs in CLOCK (rs3749474), ROR-b (rs3903529, rs3750420) and MTNR1A (rs131113549) were found noteworthy." (PMID 23822714, 2013). "In addition to MTNR1A, associations of MTNR1B rs3781638 and rs10765576 with osteoporosis and breast cancer, respectively, have been reported." (PMID 29163852, 2017). "Apparently, the impact of MTNR1A and MTNR1B receptor polymorphisms on breast cancer development and progression might be modulated by distinct endogenous and exogenous factors, e.g., ethnic differences, age, menopausal status, individual chronotype, exposure to night shift-work and light pollution." (PMID 35008896, 2021). "Also, the increased incidence of breast cancer associated with the melatonin pathway genes is thought to be due to melatonin binding to and activation of MT1 and MT2, the melatonin receptors encoded by the MTNR1A and MTNR1B genes, triggering anti-oncostatic actions in human breast cancer cells." (PMID 31358835, 2019). "Furthermore, forced expression of MTNR1A in cells led to growth suppression, suggesting that loss of MTNR1A activity plays a role in the pathogenesis of OSCC; similar results have also been found in breast cancer cell lines and in prostate epithelial cells." (PMID 24252460, 2013).
breast carcinoma (continued). "Additionally, MTNR1A rs13113549 variant has not been associated with increased breast cancer risk in a large cohort of Norwegian nurses, but its recessive homozygous genotype exerts protective influence on cancer risk in individuals with three consecutive night shift per month." (PMID 35008896, 2021).
sleep disorder (7 papers, 2021 to 2025). A change from the patient's baseline sleeping pattern, in the hours slept and/or an alteration/dysfunction in the stages of sleep. "MTNR1A has previously been implicated in several inflammatory and endocrine-related disorders, such as polycystic ovary syndrome and sleep disorders, both of which share mechanistic pathways with acne, including hormonal imbalance and immune dysregulation." (PMID 40705802, 2025). "Mutations in the Acetylserotonin O-Methyltransferas (ASMT), Melatonin Receptor 1A (MTNR1A), and Melatonin Receptor 1B (MTNR1B) genes can induce sleep disorders in ASD patients by affecting melatonin production and utilization." (PMID 37200906, 2023). "Melatonin receptor 1A (MTNR1A) is one of the receptors for melatonin to exerts it neuroprotective function in sleep disorders." (PMID 34603030, 2021). "The effect of MTNR1A on Cocaine LU may provide a window into the interaction between sleep disorders and cocaine use, especially considering that it was also significant in a cross-ancestry meta-analysis." (PMID 40736093, 2025).
type 2 diabetes (7 papers, 2021 to 2026). "The systemic involvement of MTNR1A downregulation in cancer, fetal growth restriction, type 2 diabetes, and Parkinson's and Alzheimer's diseases is further underlined by its established biological functions." (PMID 42139078, 2026). "We have recently reported the linkage and linkage plus association of variants in MTNR1A with familial type 2 diabetes and in MTNR1B with familial type 2 diabetes and type 2 diabetes-depression comorbidity." (PMID 38217063, 2024). "Most of them addressed the association with type 2 diabetes (T2D) or gestational diabetes and evaluated the gene encoding MTNR1B, even though MTNR1A has been described as a major mediator of melatonin actions." (PMID 38549765, 2024). "We have recently reported the association of variants in MTNR1A and MTNR1B genes with familial type 2 diabetes." (PMID 38217063, 2024). "The purpose of this study is to investigate the association of rotating night shift work, CLOCK, MTNR1A, MTNR1B genes polymorphisms and their interactions with type 2 diabetes among steelworkers." (PMID 37138267, 2023). "The interaction between MTNR1A gene rs2119882 locus and CLOCK gene rs1801260 locus was associated with the risk of type 2 diabetes (RERI = 1.07, (95% CI, 0.23–1.91); AP = 0.77, (95% CI, 0.36–1.17))." (PMID 37138267, 2023). "Moreover, there was a positive gene–gene interaction between CLOCK gene rs1801260 locus and MTNR1A gene rs2119882 locus on type 2 diabetes." (PMID 37138267, 2023). "In addition, there is little epidemiological evidence about the interaction between CLOCK, MTNR1A, MTNR1B genes polymorphisms and shift work on type 2 diabetes." (PMID 37138267, 2023). "Thus, from the perspective of population epidemiology, this study aims to explore the association of rotating night shift work, CLOCK, MTNR1A, MTNR1B genes polymorphisms and their interactions with type 2 diabetes among steelworkers through a case–control study." (PMID 37138267, 2023). "MTNR1A and MTNR1B are the main melatonin receptors in humans, and abnormal variants of them would trigger aberrant changes in melatonin that may contribute to the pathogenesis of type 2 diabetes." (PMID 37138267, 2023). "For instance, the role of MTNR1A and MTNR1B, THADA, CAPN10, and PPAR-γ2 in pathology of type 2 diabetes and obesity has been confirmed." (PMID 34949963, 2021).
oral squamous cell carcinoma (6 papers, 2012 to 2019). "There is also evidence that its oncostatic effects are dependent on the MTNR1A receptor, and that the tumor suppressive effect of the MTNR1A gene is silenced in oral squamous cell carcinoma." (PMID 27023475, 2016). "It has been hypothesized that in human cancers, including oral squamous cell carcinoma MTNR1A is a target for epigenetic silencing and that DNA methylation of 5’-CpG islands is a major cause of tumor-suppressor gene inactivity." (PMID 31319607, 2019). "It has been hypothesized that exogenous restoration of MT1 (MTNR1A) expression inhibits the growth of oral squamous cell carcinoma cells lacking the expression of the receptor." (PMID 24944644, 2014).
insomnia (5 papers, 2018 to 2025). A sleep disorder characterized by difficulty in falling asleep and/or remaining asleep. "The melatonin receptor Mtnr1a is differentially expressed in the hypothalamus and has links with circadian rhythms and also with exhaustion in shift workers, insomnia in schizophrenics, and with Alzheimer’s." (PMID 32116548, 2020). "In another study with a larger sample of Korean patients and a healthy control group, the presence of insomnia was associated with rs2119882 polymorphism of MTNR1A gene (Melatonin Receptor 1A), while hypersomnia did not correlate with any MTNR1A polymorphism." (PMID 29587340, 2018). "The docking results of GABRA1 with naringenin and hesperidin, HCRTR1 with naringenin-7-O-glucoside, poncirenin and genipin 1-gentiobioside, and luteolin with SLC6A4, GLO1, MAOB and MTNR1A may clarify the mechanism of action of ZZHPD in treating insomnia and depression." (PMID 35095537, 2021). "In an analysis of clinical phenotypes, rs2119882 of the MTNR1A gene was associated with insomnia in schizophrenia, but not with hypersomnia, which suggests that melatonin may be a potential target for patients with insomnia." (PMID 35225953, 2022).
polycystic ovary syndrome (5 papers, 2017 to 2025). A disorder that manifests as multiple cysts on the ovaries. "A significant association of MTNR1A gene polymorphism (rs2119882) with another comorbidity of metabolic syndrome, polycystic ovary syndrome has been reported." (PMID 29156748, 2017). "Another study has implicated MTNR1A gene variations as a risk component in polycystic ovary syndrome." (PMID 29156748, 2017). "Although MTNR1A variants have not been directly associated with T2D, a few studies have reported an association of MTNR1A variants with polycystic ovary syndrome (PCOS)." (PMID 31379753, 2019).